SP1 (Sp1 transcription factor)
Diseases named in the same sentence as SP1 in open-access papers (continued):
Sharing a sentence is not in itself a finding about the gene and the disease.
cancer (continued). "Notably, among the 14 TFs whose binding sites were sex-dependently enriched across different cancers, eight were previously found to be enriched among sex-biased expressed genes, including SP1, ETV1, ELF1, E2F1, CREB1, CTCF, SIX2, and SOX2." (PMID 39716176, 2024). "Protein stability analysis demonstrated that FT671 significantly promoted the degradation of both SP1 and β-Catenin in A549 cancer cells, indicating this may be one of the mechanisms for decreased SP1 by USP7 inhibition." (PMID 37946202, 2023). "The importance of HIF-1 and SP1 in cancer development is beyond dispute." (PMID 37998757, 2023). "However, evidence suggests a specific role for SP1 in regulating genes’ hallmarks of cancer and genes required for development and differentiation." (PMID 37189636, 2023). "Patients with higher levels of Sp1 have a worse prognosis in several cancer types." (PMID 37373974, 2023). "Transcription factors modulate the telomerase activity in cancer cells: The hTR gene promoter is activated by NF-Y, Sp1, pRB and HIF1; it is suppressed by Sp3 and signaling pathways such as JNK that cause a switch from Sp1 to Sp3 promoter binding." (PMID 37679807, 2023). "Moreover, Bcl2 and Sp1, which are miR-200b targets, were increased in cancer-derived endothelial cells when compared with healthy ECs that are characterized by very low miR-200b expression." (PMID 37261072, 2023). "It has become increasingly clear that SP1 plays a critical role in cancer progression." (PMID 36964266, 2023). "From these studies, Sp1-mediated downstream protein expression could modulate multiple signaling pathways that regulate tumorigenesis and metastasis of multiple cancers, including RCC." (PMID 36840005, 2023). "With few exceptions, lncRNA/miRNA pathways that lead to higher expression of Sp1, Sp3 and Sp4 result in downstream activation of pro-oncogenic genes/pathways, indicating that drugs targeting ncRNAs or Sp TFs should be highly effective anti-cancer agents." (PMID 36982239, 2023). "Data showed that UA suppressed the expressions of the proteins Sp-1, widely overexpressed in neoplasms, and Lin28a, the transcriptional target of Sp-1 that could elevate the levels of certain cancer-related miRNAs." (PMID 36673365, 2023). "Furthermore, Deng and colleagues showed that glucose-derived AGEs are elevated in the serum of CRC+ T2DM patients to activate the RAGE/ERK/SP1/matrix metallopeptidase-2 (MMP2) cascade reaction in cancer tissues to promote CRC invasion and metastasis." (PMID 36890832, 2023). "UA has also been suggested to inhibit proliferation signaling pathways including Ras/MAPK, PI3K/Akt, and STAT3, downregulate the apoptosis inhibitor X-linked inhibitor of apoptotic protein (XIAP), and suppress the transcription factor Sp1 (which is a poor prognostic factor for many cancers)." (PMID 37376594, 2023). "Genomic studies on these transcription factors and genes/pathways regulated by Sp1, Sp3 and Sp4 demonstrate their role in the growth, survival and migration/invasion of cancer cells and tumors, and this is consistent with their designation as non-oncogene addiction genes." (PMID 36982239, 2023). "There is only one report implicating that NPM3 might engage in cancer proliferation as a novel target of transcription factor SP1 in Hela cells." (PMID 37254219, 2023). "SP1 was significantly increased in LUAD tissues as compared to para-carcinoma tissues." (PMID 36964266, 2023). "Sp1 is overexpressed in various cancers and has the potential to be a chemotherapeutic drug target." (PMID 35744941, 2022). "SP1 appears to have a role in cancer growth, invasion, and metastasis, according to new findings." (PMID 36005140, 2022). "Sp1, an important transcription factor, is involved in the progression of various cancers." (PMID 35034634, 2022). "The expression of Sp1 is higher in most cancer cells and tissues than in normal cells and tissues." (PMID 35034634, 2022).
cancer (continued). "Searches of relevant articles indicated that SP1 can regulate NF‐κB activation in cancer." (PMID 36071548, 2022). "Furthermore, down-regulation of Sp1 inhibited tumor formation, cancer cell growth, and cell metastasis." (PMID 35869499, 2022). "Normally, Sp1 and Sp3 are ubiquitously expressed in cells, and Sp4 expression is restricted to neuronal cells where it acts as a transcription activator; however, Sp4 expression has been found in many cancer cell lines such as the LNCaP." (PMID 35018219, 2022). "Sp1, a transcription factor that binds to the Mcl-1 promoter region, has already been tested and found to play important physiological roles, such as in apoptosis, by targeting Mcl-1 in cancer." (PMID 35524332, 2022). "Taken together, Sp1 decreases stemness characteristics and thus may block drug resistance and inhibit cancer malignancy." (PMID 35034634, 2022). "SP1 functions as an oncogene in various cancer, including OSCC." (PMID 35237504, 2022). "A further study revealed that expression of miR-200b, by direct targeting SUZ12 and through histone deacetylase 1/Sp1/miR-200b signaling pathway might lead to the formation of chemoresistant phenotype in docetaxel-resistant cancer cells." (PMID 36158660, 2022). "In addition, as a cancer-promoting factor, Sp1 is overexpressed in thyroid cancer, gastric cancer, pancreatic cancer, glioma, and breast cancer, leading to poor prognosis." (PMID 36305724, 2022). "Given the role of SP1 in responding to DNA damage — which would be present in both UVB-irradiated cells and cancer — we hypothesized that SP1 might directly mediate the induction of Mmp2 and Mmp11 mRNA by UVB." (PMID 35316219, 2022). "In addition, further studies also reported Sp1 regulates the inflammation and the immune cell infiltration of cancers." (PMID 35778451, 2022). "If Fuc-Hp plays a role in promoting cancer progression, the inhibition of Fuc-Hp production or function may have therapeutic potential, and SP1 inhibition may represent a potential treatment option." (PMID 36313594, 2022). "SP1 is a nuclear transcription factor participating in many cellular processes, such as differentiation, proliferation and apoptosis, and it is highly expressed in many cancers and usually correlated with poor prognosis." (PMID 35590288, 2022). "Strengthening the link between Sp1 and chromosome segregation errors would position Sp1 as a biomarker for chromosome segregation errors in human cancers, which may result in more precise and effective therapeutic interventions." (PMID 35916925, 2022). "In addition to cancer cells, Sp1 can transcriptionally regulate T-BET expression, a main regulator of IFN-γ, in NK cells and T cells." (PMID 35778451, 2022). "The promoting effect of axes HOXA11-AS/miR-124/EZH2 (enhancer of zeste homolog 2 of polycomb group protein), HOXA11-AS/miR-124-3p/ITGB3 (integrin β3), and HOXA11-AS/miR-124/Sp1 (Sp1 transcriptional factor) on cancer cell proliferation, migration, invasion was shown in vitro." (PMID 36362406, 2022). "In addition, previous studies have indicated that posttranslational modification of Sp1 is important for regulating its transactivity and protein degradation, which are involved in physiological and pathological conditions such as cancer progression." (PMID 35034634, 2022). "Sp1 is an important transcription factor that regulates the expression of many genes involved in various physiological and pathological conditions, such as cancer progression." (PMID 35034634, 2022). "Levels of EGFR were found to be reduced in Sp1-knockdown or Sp3-knockdown cancer cells." (PMID 36615262, 2022). "And BHLHE40 facilitates the invasion of cancer cell by interacting with SP1." (PMID 36463222, 2022). "Sp1 can upregulate VEGF to promote cancer cell growth, angiogenesis, and metastasis, downregulation of miR-22 upregulated by these polyphenols may contribute to the anticancer effects of these polyphenols." (PMID 35744941, 2022).
cancer (continued). "Numerous studies on Sp1 in various cancer cells have been reported." (PMID 34531430, 2021). "Therefore, SP-1 seems to be a promising therapeutic compound to treat angiogenesis-related diseases or cancer." (PMID 34572295, 2021). "It has been confirmed that SP1 can regulate a variety of cancer-related genes." (PMID 34257529, 2021). "Based on this point, SP1 has the potential to become a target to treat cancers." (PMID 34257529, 2021). "Correspondingly, the blockade of BRAFV600E/ERK signaling could reduce the recruitment of p-Sp1 to TERT promoter, indicating that p-Sp1 may be involved in ERK-induced GABPA binding in cancer cells." (PMID 33483600, 2021). "SP1 is a transcription factor known to regulate the expression of multiple oncogenes related to cell proliferation, cell cycle, and metastasis, thus contributing to cancer development including HCC29." (PMID 34285329, 2021). "Various treatments and drugs targeting SP1 have been investigated to cure cancers." (PMID 34970121, 2021). "Considering that Sp1 dominates the expression of many important genes during tumor development, targeting Sp1 may offer novel therapeutic tools for cancer treatment." (PMID 33472586, 2021). "In fact, The SP1 hypothesis for AD intervention originated from cancer research as SP1 is upregulated in various types of cancer." (PMID 33809987, 2021). "In addition, Sp1 expression levels are higher in cancer cells than in normal cells, and the growth and metastasis of cancer cells are weakened in nude mice in which Sp1 is knocked out44,45." (PMID 34531430, 2021). "In addition, several studies have shown that Sp1 induces cancer metastasis by regulating the expression of CD147 or affecting EMT by upregulation of SNAIL expression, which also supports our findings." (PMID 33771199, 2021). "Even though Sp1-controlled transcription has been viewed historically as a prominent target of mithramycin, ultimately, the effect of mithramycin on cancer cells is likely to be an indirect consequence of perturbing the function of Sp1 or some other transcription factor." (PMID 33445667, 2021). "Given that p-Sp1 and GABPA can be recruited to mutant TERT promoter with high cooperativity, thus we suppose that Sp1 and GABPA synergistically activate mutant TERT promoter in cancer cells carrying both BRAFV600E and TERT promoter mutations." (PMID 33483600, 2021). "Notably, accumulating evidence shows that Sp1 plays a critical role in the inflammatory signalling that mediates cancer-stroma cross-talk." (PMID 33484377, 2021). "Additionally, the targeting of Sp1 as a cancer treatment has been suggested; however, the role of Sp1 in malignancy is complex." (PMID 33895141, 2021). "However, Sp1 is drawing attention due to its potential role as a predictor of survival in many types of cancer including GC." (PMID 34202606, 2021). "The results highlight the possibility of SP1 becoming a clinical target of some specific cancers." (PMID 34257529, 2021). "Notably, BCL2L1, E2F1, HRAS, MAPK8, MITF, RELA, and SP1 were found in both mitophagy and cancer pathways." (PMID 34262589, 2021). "Importantly, there is evidence that SP-1 plays a role in cancer progression, invasion and metastasis." (PMID 34876130, 2021). "A well-documented function of Sp1 is in cell proliferation of cancer." (PMID 34830324, 2021). "Moreover, SP1 was shown to be the main target of delivered miRs in leukemic and other cancer models." (PMID 33498689, 2021). "Both MYC and SP1 expression correlate with TERT transcription in various cancer cell lines." (PMID 33802026, 2021). "This review highlights the drugs targeting Sp1 and their action on cancer cells." (PMID 32050495, 2020). "SP1 and other family members are proved overexpressed in kinds of cancers." (PMID 32158359, 2020). "Interestingly, Sp1 is overexpressed in several cancers, such as breast, pancreatic, lung, glioma, and thyroid." (PMID 33171624, 2020).
cancer (continued). "So, it is still unclear whether SP1 plays a dual role in the development of cancer, which requires further investigation." (PMID 31892989, 2020). "However, Sp1 would be a weak candidate for a biomarker of cancer‐specific TERT expression because of its ubiquitous expression in normal cells." (PMID 33329574, 2020). "In tumorigenesis, Sp1 facilitates cancer progression by activating the expression of many oncogenes that play pivotal roles in the metabolism, proliferation, and metastasis of various cancer cells." (PMID 32326583, 2020). "Parallel to this, icotinib in combination with BDMC caused marked decrease of EGFR activity through depressing Sp1 and the interaction of Sp1 and HDAC1/HDCA2, consequently diminishing protein and mRNA expressions of HDAC1/HDCA2 which are the key regulators for cancer development and growth." (PMID 32226300, 2020). "Sp1, usually overexpressed in many human tumors and cancer cell lines, plays an important role in tumorigenesis and cancer progress and is a potential target for development of drugs in cancer chemotherapy." (PMID 32851058, 2020). "SP1 play major roles in the pathogenesis of various cancers." (PMID 31823440, 2020). "Sp1 is a crucial transcription factor that regulates the growth of cancer cells." (PMID 32160655, 2020). "Moreover, our result also indicated important roles of SP1, a well‐known transcription factor that has been shown to be involved in the proof of concept functions in cancer biology." (PMID 31823440, 2020). "Regulation of Sp1 activity should be an effective strategy for cancer drug screening." (PMID 32851058, 2020). "Overexpression of the Sp1 TF has been shown to lessen the level of apoptosis in cancer cells." (PMID 32050495, 2020). "For many cancer patients, elevated Sp1 expression is considered as an adverse prognostic factor." (PMID 33230457, 2020). "We also showed that TMPRSS4 upregulates the expression of the urokinase-type plasminogen activator (uPA) gene through activator protein-1 (AP-1) and Sp1/3 transcription factors and induces processing of pro-uPA into the active form to promote cancer cell invasion." (PMID 31292507, 2019). "Thus, SP1 activity is required to enhance cell migration downstream of the aberrant activation of the WNT/PCP/JNK pathway in basal-like cancer cells, at least partly via the induction of RHOU expression." (PMID 30654518, 2019). "The ERE (−84/49), activator protein 1 (−149/−129), and SP-1/XRE (−853/−824) transcription factor-binding sites in the human CYP1B1 promoter are important for regulating the transcription of CYP1B1 in cancer cells." (PMID 31775380, 2019). "Thus, several ongoing clinical trials are attempting to block PI3K/AKT/SP1 pathway activation using specific inhibitors to attenuate cancer cell proliferation, cell migration, and tumor invasion." (PMID 30914776, 2019). "Also miR-199a-3p can inhibit LDHA expression (by downregulating the Specificity protein 1 (Sp1)-transcription factor), which supports the critical contribution of a miR-199a-3p/Sp1/LDHA axis to aerobic glycolysis in cancer cells." (PMID 31035592, 2019). "Ajuba is a newly defined transcriptional co-regulator and plays important role in various cancers development, while SP1 is a classic transcription factor, and is closely related with a variety of gene expression regulation and cancer development including PDAC." (PMID 31101117, 2019).
cancer (continued). "Similarly, previous experiments demonstrated that TRAIL-mediated Sp1 activation increases the sensitivity of cancer cells to apoptosis through the upregulation of DR5 expression." (PMID 29535810, 2018). "Specificity protein 1 (SP1) is highly expressed in several cancers including CRC and is correlated with poor prognosis, but it is unclear whether or not MIR-382 can regulate the expression of SP1." (PMID 30474556, 2018). "Thus, Sp1 activation is an important target in TRAIL-resistant cancer cells to strengthen its sensitivity through upregulation of DR5 by binding to the transcription start sites of DR5." (PMID 29535810, 2018). "SP1 has been found to be regulated by multiple miRNAs in several human cancers." (PMID 30474556, 2018). "The involvement of Sp1 in cancer metabolic rewiring has been further shown in different reports." (PMID 29865240, 2018). "Assembling evidences suggested that SP1 involved in cancer biology." (PMID 29614984, 2018). "Elevated expression of SP1 was identified in several human cancers." (PMID 30474556, 2018). "In particular, we aimed to determine whether cooperation between ZEB2 and Sp1 promotes cancer cell survival and paracrine activation of endothelial cells." (PMID 29416649, 2018). "Because of the crucial role of PDPK1 downstream PI3‐K/Akt pathway in cancer growth and progression 21, 40 and the reported links of the Akt in regulation of SP1 and DNMT1 expressions in several cancer types in other studies 33, 38, 41, we then assessed the role of Akt signalling in this process." (PMID 28840963, 2018). "We observed that the promoter sequences of these translation elongation factor genes harbour binding sites for transcription factors which are commonly deregulated in the pathogenesis of human cancers, such as cFos, cJun, c-Ets1, Sp1, Sp3, Pax2 and, Pax6 among others." (PMID 29342219, 2018). "In a number of cancers, miRNAs regulated cell proliferation and metastasis by targeting Sp1." (PMID 28422727, 2017). "The role of the SP transcription factor family in different cancers has already been highlighted, and there is evidence that overactivation of SP1 occurs frequently in a wide variety of different tumors, correlating with aggressive biology and poor clinical outcome of these tumors." (PMID 29046731, 2017). "Sp1-induced transcription of protein coding genes has been extensively studied in human cancers." (PMID 28422727, 2017). "This study supports the possibility of regulating transcription factor Sp1 in cancer cells by treatment with atmospheric-pressure plasma, which could represent a potential application in anticancer therapy." (PMID 28225083, 2017). "Cancer cell type specific co-regulators included SP1, NCOA1, NCOA2, and PIAS1." (PMID 28117763, 2017). "The level of Sp1 expression is higher in cancer cells than in normal cells." (PMID 28225083, 2017). "In addition, other transcription factors like STAT5, Sp1, and β-Catenin that potentially contribute to cancer progression signaling have been reported to bind at the promoter region of miR-182." (PMID 28122586, 2017). "The interaction between miR-22 and Sp1 has been reported in many cancers." (PMID 28422727, 2017). "SP1 is considered as a carcinogenic regulator and a potential target for cancer chemotherapy." (PMID 28165192, 2017). "In addition to a direct increase in transcriptional activity, many additional strategies for the regulation of Sp1 expression during cancer progression have been reported." (PMID 28831131, 2017). "SP1 also positively participates in the invasion in various cancers." (PMID 29163762, 2017). "Furthermore, previous studies demonstrate the role of SP1 as a transcription factor of DNMT1 gene in several human cancer cells and mouse NIH3T3 cells." (PMID 29163762, 2017).